VIP (vasoactive intestinal peptide)
Diseases named in the same sentence as VIP in open-access papers (continued):
Sharing a sentence is not in itself a finding about the gene and the disease.
Hypoglycemia (3 papers, 2017 to 2022). A decreased concentration of glucose in the blood. "Several studies have demonstrated that the specific binding of VIP with VPAC2 receptors on β-cells can stimulate insulin secretion in a glucose-dependent manner, eliminating the risk of hypoglycemia." (PMID 36204104, 2022). "Therefore, VIP may act as an insulinotropic drug without increasing the risk of hypoglycemia following administration." (PMID 36204104, 2022). "Hypoglycemia has not yet been identified in these models, which means that VIP induces insulin secretion in a glucose-dependent manner." (PMID 36204104, 2022).
Infertility (3 papers, 2009 to 2024). "Our data reveal previously unknown and useful information about VIP's contribution to uterus receptivity, embryo implantation, and peri-implantation period that might be relevant to understand infertility associated with an endometrial factor." (PMID 31969877, 2019). "Understanding the mechanisms by which PACAP and VIP influence male fertility can help in identifying potential biomarkers for diagnosing infertility." (PMID 38674298, 2024). "For instance, targeting PACAP or VIP signaling pathways in combination with other therapies could offer synergistic effects and improve treatment outcomes for men with infertility issues." (PMID 38674298, 2024).
intestinal obstruction (3 papers, 2015 to 2026). Blockage of the normal flow of the intestinal contents within the bowel. "Changes in VIP expression have the potential to alter motility and nutrient absorption in the small intestine which can result in intestinal obstruction, a common complication in gastrointestinal tract neoplasms." (PMID 41162835, 2026). "Previous studies suggest that the principal mechanism of fluid secretion in bowel obstruction depends on vasoactive intestinal peptide (VIP)-induced inflammatory events." (PMID 25889313, 2015). "Changes in VIP-expressing neural elements may alter motility and absorption in the small intestine and result in intestinal obstruction, a common and severe complication of inflammatory and neoplastic diseases in the gastrointestinal tract." (PMID 27635657, 2016).
juvenile idiopathic arthritis (3 papers, 2014 to 2020). Juvenile idiopathic arthritis (JIA) is the term used to describe a group of inflammatory articular disorders of unknown cause that begin before the age of 16 and last over 6 weeks. "Moreover, low serum levels of VIP have been described in patients with juvenile idiopathic arthritis who show clinical evidence of cardiac autonomic neuropathy associated with a parasympathetic dysfunction." (PMID 24409325, 2014). "Moreover, patients with juvenile idiopathic arthritis have lower serum levels of VIP than healthy controls." (PMID 24409325, 2014).
lung carcinoma (3 papers, 2022 to 2024). "Lung cancer cell proliferation was stimulated at low VIP doses (10 nM) while cancer growth was suppressed by high VIP doses (100 nM and 1 μM)." (PMID 35011543, 2022). "Furthermore, the overexpression of VIP and its receptors was previously reported in breast, prostate, and lung cancers, wherein VIP promotes growth and metastasis in tumors." (PMID 38673976, 2024).
medullary thyroid carcinoma (3 papers, 2021 to 2025). "The accelerated time course of WDHA syndrome is a feature of VIP-secreting PHEO compared to pancreatic islet cell tumor, bronchogenic carcinomas, and medullary thyroid carcinomas secreting VIP." (PMID 33815297, 2021).
polycystic ovary syndrome (3 papers, 2014 to 2025). A disorder that manifests as multiple cysts on the ovaries. "In patients with polycystic ovary syndrome (PCOS), VIP levels are significantly elevated, which may be related to the increased density of sympathetic nerve fibers in the ovaries of PCOS patients." (PMID 41091826, 2025).
Pruritus (3 papers, 2007 to 2021). Pruritus is an itch or a sensation that makes a person want to scratch. "Keratinocytes in thepsoriatic plaques of patients with pruritus also showed consistently increasedexpression of SP receptor, TrkA and CGRP receptor, but the immunoreactivity forSP, CGRP, VIP, and PACAPwas independent on the occurrence of pruritus." (PMID 18288273, 2007). "Moreover, significant, negativecorrelations between pruritus severity and SP as well as VIP plasma levels werefound." (PMID 18288273, 2007). "Recently, the sensitive skin, a syndrome associated with pruritus, has been characterized as a small fiber neuropathy while, in atopic dermatitis (AD) and psoriasis, two pruritic dermatoses, an increase of GRP+, SP+, VIP+, and CGRP+ cutaneous fiber nerves has been clearly demonstrated." (PMID 34923994, 2021). "These CNF contain neuropeptides such as substance P (SP), calcitonin gene-related peptide (CGRP), vasoactive intestinal peptide (VIP), and gastrin-releasing peptide (GRP), known to be inducers and potentializers of pruritus." (PMID 34923994, 2021).
pulmonary fibrosis (3 papers, 2017 to 2025). Chronic progressive interstitial lung disorder characterized by the replacement of the lung tissue by connective tissue, leading to progressive dyspnea, respiratory failure, or right heart failure. "Although VIP has been shown to mitigate bleomycin-induced pulmonary fibrosis by restoring autophagy in alveolar epithelial cells, its role in hematologic malignancies remains unexplored." (PMID 40873580, 2025). "Unlike the other neuropeptides (CGRP, SP and VIP), NPY is a vasoconstrictor and also promotes angiogenesis and blocked generation of pulmonary fibrosis through inhibition of IL-1β." (PMID 38183438, 2024).
Secretory diarrhea (3 papers, 2023 to 2025). Watery voluminous diarrhea resulting from an imbalance between ion and water secretion and absorption. "Vasoactive intestinal peptide (VIP)–secreting tumours are a rare cause of secretory diarrhoea with an incidence of 1 in 10 million people per year." (PMID 41195063, 2025). "VIP is now widely accepted as a major mediator of watery diarrhea syndrome, and VIP overexpression leads to secretory diarrhea." (PMID 37218372, 2023). "Several neurotransmitters, including vasoactive intestinal peptide (VIP) and nitric oxide (NO) secreted by neuronal nitric oxide synthase (nNOS) neurons, have been shown to be upregulated during the progression of secretory diarrhea." (PMID 36830577, 2023).
small cell lung carcinoma (3 papers, 2018 to 2022). Small cell lung cancer (SCLC) is a highly aggressive malignant neoplasm, accounting for 10-15% of lung cancer cases, characterized byrapid growth, and early metastasis. "For instance, an early study revealed that VIP inhibits small cell lung cancer (SCLC) progression in vitro and in vivo via the activation of the cAMP/PKA pathway." (PMID 35864952, 2022). "BB, NTS, and VIP stimulate the growth of small cell lung cancer (SCLC) cells whereas SST inhibits growth." (PMID 30008698, 2018).
acromegaly (2 papers, 2020 to 2024). Acromegaly is an acquired disorder related to excessive production of growth hormone (GH) and characterized by progressive somatic disfigurement (mainly involving the face and extremities) and systemic manifestations. "It is used to treat acromegaly and alleviate symptoms associated with metastatic carcinoid tumors (flushing and diarrhea) and vasoactive intestinal peptide (VIP)-secreting adenomas (watery diarrhea)." (PMID 38473389, 2024). "Sandostatin LAR (octreotide) is another long acting somatostatin analog approved by the FDA for treatment of acromegaly, severe diarrhea/flashing episodes associated with metastatic carcinoid tumors, and vasoactive intestinal peptide (VIP) secreting tumors." (PMID 32435228, 2020).
adenocarcinoma of the pancreas (2 papers, 2020 to 2023). "We next analyzed associations between VIP and ZEB1 expression in the human stomach, colon, esophageal, and pancreatic adenocarcinoma cell lines from the CCLE (cancer cell line encyclopedia) using the DepMap resource." (PMID 37444395, 2023). "Skin metastasis has been mostly reported in adenocarcinoma of the pancreas, but other histological subtypes have also been associated with cutaneous spread–adenosquamous cell carcinoma, mucinous cystadenocarcinoma, neuroendocrine carcinoma or VIP (vasoactive intestinal polypeptide) tumor." (PMID 32806580, 2020).
adenoma (2 papers, 2016 to 2024). A neoplasm arising from the epithelium. "It has been used to treat symptoms associated with both metastatic neuroendocrine tumors and vasoactive intestinal peptide (VIP) secreting adenomas." (PMID 27992479, 2016).
allergic conjunctivitis (2 papers, 2011 to 2021). "Specifically, it has been demonstrated that neuropeptides, including substance P, calcitonin-gene-related peptide (CGRP), neuropeptide Y (NPY), and vasoactive intestinal peptide (VIP), play a key role in allergic conjunctivitis." (PMID 34685384, 2021).
Cachexia (2 papers, 2016 to 2024). Severe weight loss, wasting of muscle, loss of appetite, and general debility related to a chronic disease. "This may reflect changes in VIP-IR neurons in the submucosal plexus, as demonstrated in this model of cachexia." (PMID 38607556, 2024). "As for VIP-IR varicosities, hypertrophic CGRP-containing varicosities were associated with higher CGRP expression, implying an adaptive response to systemic effects of cachexia." (PMID 27635657, 2016). "Therefore, in the current study the decrease in neuronal density of the pan neuronal population (HuC/D-IR) and ChAT-IR and VIP-IR subpopulations may result from systemic effects of cachexia, mediated by oxidative stress." (PMID 27635657, 2016). "However, defects in axonal transport of VIP, common in neurodegenerative processes, may be present in cachexia and lead to accumulation of this neuropeptide in varicosity." (PMID 27635657, 2016). "However, there have been isolated cases in which an unexpected abnormal neuron hypertrophy and a slight increase in the size of VIP- and CGRP-containing varicosities were noted when the diets of healthy or cachexia rats were supplemented with l-glutamine." (PMID 27635657, 2016). "Therefore, a complementary investigation to this study evaluated the morphometry of VIP and CGRP-containing nerve fibers and morpho-quantitative changes in VIP-containing neurons of the small intestine in a cancer cachexia experimental model." (PMID 27635657, 2016).
clear renal cell carcinoma (2 papers, 2020 to 2022). "In clear renal cell carcinoma (cRCC), some studies suggest that the proliferation-inhibitory role of VIP/VIPR1 signaling is related to the activation of EPAC/PI3K pathway." (PMID 35864952, 2022). "Similarly, Epac exhibits an anti-proliferative role in clear renal cell carcinoma in mediating vasoactive intestinal peptide (VIP)-induced inhibition of cell proliferation through the PI3K pathway." (PMID 32899451, 2020).
complication (2 papers, 2022 to 2023). Any disease or disorder that occurs during the course of, or because of, another disease, treatment, or procedure. "In this study, we investigated the potential therapeutic efficacy of Tβ4/VIP in mitigating diabetic corneal complications by evaluating its effects on corneal epithelial barrier function and wound healing." (PMID 37998149, 2023).
cystic fibrosis (2 papers, 2023). Autosomal recessive disorder caused by pathogenic variants in the CFTR gene (cystic fibrosis transmembrane conductance regulator), which encodes a chloride and bicarbonate channel expressed in epithelial cells, and follow the diagnosis criteria. "Interestingly, in cystic fibrosis, synergistic airway mucus secretion induced by VIP and carbachol stimulation is lost, suggesting this could be of interest for further investigation with the Capan-1 model, concerning CF-associated pancreatic pathology." (PMID 36534232, 2023).
cystitis (2 papers, 2017 to 2021). Inflammation of the urinary bladder. "Quantitative PCR was used to determine NGF, BDNF and receptors (TrkA, TrkB, p75NTR) and PACAP/VIP and receptors (PAC1, VPAC1, VPAC2) transcripts expression in LUT tissues from NGF-OE and WT mice with CYP-induced cystitis (4 h, 48 h, and chronic)." (PMID 29255407, 2017).
developmental delay (2 papers, 2012 to 2022). "In a previous study, VPAC1−/− mice were observed to have developmental delays with lower body weight, similarly to VIP null mice, with significantly lower body weights observed in 4-week-old VPAC1−/− male and female pups, compared to WT and heterozygous mice." (PMID 35336804, 2022). "Active fragments of neurotrophic factors release by astrocyte under the stimulation of vasoactive intestinal peptide, NAPVSIPQ (NAP) and SALLRSIPA (SAL) respectively, have shown therapeutic potential for developmental delay and learning deficits." (PMID 23209818, 2012).
Dravet syndrome (2 papers, 2024). "For instance, VIP+ interneurons in Dravet Syndrome show altered action potential generation and impaired network dynamics, leading to behavioral symptoms but not necessarily seizures." (PMID 39916937, 2024). "In Dravet Syndrome animal models, VIP+ interneurons exhibited abnormal action potential generation due to reduced Nav1.1." (PMID 39916937, 2024). "Conversely, NDNF+ interneurons showed normal Nav1.1 expression and activity in these mouse models, underscoring the distinct roles of different interneuron types in animal models that mimic some symptoms of Dravet Syndrome and highlighting VIP+ interneurons as potential future therapeutic targets." (PMID 39916937, 2024). "Notably, VIP interneuron-specific SCN1A deletions replicated a number of Dravet syndrome symptoms but did not induce seizures, suggesting that VIP+ interneurons might be involved in managing behavior and network activity." (PMID 39916937, 2024).
dry eye (2 papers, 2023 to 2025). "Based on the changes in VIP, this study reasonably explained the cause of neurogenic dry eyes after LASEK and FS-LASIK surgeries." (PMID 37081425, 2023). "In FS-LASIK and LASEK subjects, dry eyes were mainly affected by the basic ocular surface status before surgery, and VIP concentration." (PMID 37081425, 2023). "In future studies, the role of VIP in regulating dry eye in experimental verification of laser keratorefractive surgery will be verified again in animal models." (PMID 37081425, 2023). "Under adverse injury stimulation, VIP plays a neuroimmune role in regulating dry eyes, including after refractive surgery." (PMID 37081425, 2023). "Elevated post-surgery tear VIP relieves dry eye symptoms, showing its neuroimmune role in regulating adverse injury stimulation." (PMID 37081425, 2023). "This study found a significant correlation between VIP concentration and dry eye symptoms, that is, the increase in VIP under stress plays a protective role in relieving dry eye symptoms after corneal injury." (PMID 37081425, 2023). "The factors influencing dry eye at different times post LASEK and FS-LASIK surgeries, and a possible correlation between dry eye and VIP concentration were analyzed." (PMID 37081425, 2023). "The main results are as follows: dry eye symptoms were negatively correlated with tear VIP concentration, including instant VIP and increase of VIP concentrations." (PMID 37081425, 2023). "Elevated tear VIP after surgery could relieve dry eye symptoms and dry eye symptoms at different stages after surgery are highly correlated with VIP concentration and preoperative basic ocular surface status." (PMID 37081425, 2023). "Increases in VIP concentrations were correlated with dry eye indices and AD." (PMID 37081425, 2023). "Therefore, this study hypothesized that VIP, a multifactorial inflammatory factor, may regulate postoperative dry eyes." (PMID 37081425, 2023). "Therefore, in addition to VIP, CGRP probable has a protective effect in relieving dry eyes in the early stages after LASEK, which also needs further validation." (PMID 37081425, 2023).
duodenal ulcer (2 papers, 2018 to 2020). An ulcer in the duodenal wall. "An increase in PACAP as well as VIP expression is observed in enteric neurons in many experimental models such as naproxen treatment and duodenal ulcer model." (PMID 33013401, 2020).
edema (2 papers, 2022 to 2025). An abnormal accumulation of fluid beneath the skin, or in one or more cavities of the body. "In an LPS-induced SALI mouse model, emodin alleviated lung inflammation and pulmonary edema by promoting the expression of the immunoregulatory neuropeptide VIP and significantly inhibited NF-κB and MAPK phosphorylation, activating the VIP/cAMP/PKA signaling pathway." (PMID 39910395, 2025).
enthesitis (2 papers, 2015 to 2022). Inflammation at the site of insertion of ligaments, tendons, and other fibrous structures into bone. "Coexistence of cutaneous psoriasis was independently associated with lower VIP levels, and similar trend was observed for enthesitis." (PMID 25711477, 2015). "The presence of enthesitis or cutaneous psoriasis was also independently associated with lower serum VIP levels." (PMID 25711477, 2015).
fragile X syndrome (2 papers, 2023 to 2024). A genetic syndrome caused by mutations in the FMR1 gene which is responsible for the expression of the fragile X mental retardation 1 protein. "Additionally, VIP+ interneuron dysfunction has been linked to Fragile X Syndrome (FXS), which is characterized by attention deficits and hypersensitivity to sensory inputs." (PMID 39916937, 2024). "In Fragile X Syndrome, VIP interneurons show reduced modulatory influence, affecting sensory processing and task performance." (PMID 39916937, 2024).
gastric adenocarcinoma (2 papers, 2023). "In gastric adenocarcinoma tissues, the expression of VIP mRNA is upregulated, whereas that of VIPR mRNA is downregulated." (PMID 37771430, 2023). "The strong association between VIP and ZEB1 in stomach adenocarcinoma warranted further investigation." (PMID 37444395, 2023). "Notably, the strongest association observed was between VIP and ZEB1 in stomach adenocarcinoma (R = 0.76)." (PMID 37444395, 2023).
gastritis (2 papers, 2014 to 2019). Inflammation of the stomach. "In contrast, Erin and coworkers (2012) demonstrated a decreased level of VIP in human gastric mucosa during gastritis or ulcers." (PMID 24643520, 2014). "However, aspirin-induced gastritis resulted in de novo synthesis of VIP in nearly 40 % of the gastric vagal neurons." (PMID 24643520, 2014). "In summary, this study shows that ASA-induced gastritis in immature gilts results in increased expression of PACAP and de novo expression of VIP, NOS, and GAL in dorsal motor vagal neurons supplying the prepyloric region of the porcine stomach." (PMID 24643520, 2014). "This fact may be a consequence of protective function of other bioactive substances such as PACAP, VIP, NO, and GAL in ASA-supplementation-induced gastritis, but this question needs further research." (PMID 24643520, 2014).
gastroenteritis (2 papers, 2019 to 2023). An inflammatory disorder that affects the upper and lower gastrointestinal tract. "5-hydroxytryptamine (5-HT) and vasoactive intestinal peptide (VIP) are involved in rotavirus-induced gastroenteritis." (PMID 37006293, 2023).
gastroesophageal reflux disease (2 papers, 2019 to 2023). A chronic disorder characterized by reflux of the gastric and/or duodenal contents into the distal esophagus. "Study demonstrated that enriched genes including IL1B, CXCR1, FFAR4, VIP (vasoactive intestinal peptide), and GATA3 have been identified as a key candidate genes in patients with gastroesophageal reflux disease." (PMID 38137330, 2023).
Graves disease (2 papers, 2020 to 2022). Graves' disease is an autoimmune disorder that leads to overactivity of the thyroid gland (hyperthyroidism).It is caused by an abnormal immune system response that causes the thyroid gland to produce too much thyroid hormones. "Only Graves’ disease (GD) patients showed significantly lower serum VIP levels when compared to healthy subjects and to Hashimoto’s thyroiditis patients." (PMID 32747757, 2020).